RPSAP56 (ribosomal protein SA pseudogene 56)
Synonyms: RPSA_23_1496
Gene: Gene (Ensembl biotype translated_processed_pseudogene) on chromosome 16 (73,940,639 to 73,941,781, reverse strand). Ensembl gene ENSG00000284670.
Diseases named in the same sentence as RPSAP56 in open-access papers:
RPSAP56 is named in the same sentence as 1 disease in open-access papers, as found by Europe PMC text mining. Sharing a sentence is not in itself a finding about the gene and the disease.
RPSAP56 shares sentences with these, for which no sentence is quoted: viral infection (1 paper).